EP300 (EP300 lysine acetyltransferase)
Diseases named in the same sentence as EP300 in open-access papers (continued):
Sharing a sentence is not in itself a finding about the gene and the disease.
bladder cancer (23 papers, 2017 to 2026). "EP300, a frequently mutated transcriptional coactivator in bladder cancer, has been demonstrated to positively correlate with malignancy in various cancers." (PMID 42258462, 2026). "In bladder cancer, EP300 mutation was associated with higher tumor mutational burden scores and indicated a favorable clinical prognosis, which was reported to be a biomarker for immunotherapy." (PMID 40164592, 2025). "Mutational status in CREBBP and/or EP300 was associated with improved OS in selected gastrointestinal tumors and bladder cancer." (PMID 41301688, 2025). "By screening the mutations of EP300, the EP300-R1627W mutation was found that significantly impairs EP300 transactivation activity following a “gradation” pattern, which promotes the growth and invasion of bladder cancer." (PMID 40164592, 2025). "In bladder cancer, patients with EP300 mutations were associated with a positive prognosis and higher tumor mutational burden (TMB) scores, which was reported to be a biomarker for immunotherapy." (PMID 36647005, 2023). "According to the cBioPortal database, the EP300 mutation rate in bladder cancer is 16.6%, ranking first in pan-cancer analysis." (PMID 36647005, 2023). "In summary, our study demonstrated that EP300 was frequently mutated in bladder cancer, and EP300 mutation was associated with higher TMB and indicated a better prognosis." (PMID 32012118, 2020). "Bladder cancer is a genomically heterogeneous tumor with a high mutation rate, and EP300 is also a frequently mutated gene in bladder cancer." (PMID 32012118, 2020). "Somatic mutations in the EP300 gene activate the immune-regulatory signaling pathways and improve antitumor immunotherapeutic outcomes in bladder cancer patients." (PMID 33216732, 2020). "We previously identified several bladder cancer-associated mutations in EP300 using high-throughput sequencing; however, the functional consequences of these mutations remain unclear." (PMID 36647005, 2023). "EP300 as one of frequently mutated genes in the bladder cancer was significantly associated with increased TMB and enhanced antitumor immune response, which might serve as a new biomarker to predict clinical prognosis and immune response in bladder cancer." (PMID 35242279, 2022). "Even if EP300 is also frequently mutated in Chinese bladder cancer sample, the effect may be somewhat heterogeneous between different ethnic groups." (PMID 32012118, 2020). "Therefore, we found that EP300 mutation elicited the variation of infiltrated immune cells contributing to antitumor immunity in bladder cancer." (PMID 32012118, 2020). "In our study, we also found that bladder cancer samples with EP300 mutation had lower Tregs loads." (PMID 32012118, 2020). "In conclusion, EP300 is frequently mutated in bladder cancer, and its mutation is associated with increased TMB and promotes antitumor immunity, which may serve as a biomarker to predict immune response." (PMID 32012118, 2020). "The main limitation in our study is that the ICGC database lacks corresponding clinical data of Chinese bladder cancer, so we cannot verify whether EP300 mutation is associated with the prognosis of bladder cancer patients in China, and whether it can give rise to the same immune response." (PMID 32012118, 2020). "Chromatin regulation genes, including KDM6A, KMT2D, EP300, and ARID1A, show high rates of mutation in bladder cancer, as demonstrated here and in multiple cohort studies." (PMID 41373802, 2025). "On one hand, EP300 loss-of-function relieves its inhibition on IL-1α signaling, activating the IL-6/JAK/STAT3 pathway and driving bladder cancer." (PMID 40375990, 2025). "However, the function of EP300 mutations in bladder cancer remains unclear." (PMID 36647005, 2023). "In summary, our work defines a driver role of EP300-R1627W in bladder cancer development and progression." (PMID 36647005, 2023).
bladder cancer (continued). "In bladder cancer cells, experimental downregulation of EP300 also leads to doxorubicin and cisplatin resistance." (PMID 28341962, 2017). "Collectively, our findings demonstrate that EP300 promoted bladder cancer cell migration via up-regulating SNAI2, targeting EP300 could be a potential therapeutic strategy to inhibit the process of bladder cancer invasion." (PMID 42258462, 2026). "Zhu and his colleagues found that EP300 mutation could induce antitumor immunity and upregulate TMB in bladder cancer." (PMID 36276071, 2022). "For example, one could envision a trial of a combination of a checkpoint inhibitor with a BET inhibitor in bladder cancers with high TMB and EP300 mutations, while patients with high TMB and DNA damage response defects could be assigned to a checkpoint inhibitor with PARP inhibitor arm." (PMID 35323317, 2022). "UCA1, which is overexpressed in bladder cancer, specifically induces Glutaminase 2 (GLS2) by sponging miR-16, and can also activate AKT by recruiting E1A Binding Protein P300 (EP300) and lead to bladder cancer cell growth." (PMID 34422802, 2021). "In bladder cancer, it was confirmed that lncRNA KTN1 AS1 overexpression promotes the recruitment of a histone acetyltransferase EP300." (PMID 34219129, 2021). "Therefore, the upregulation of EP300, PTPN11, and RAC1 genes may play a role in the development of NDV persistent infection in EJ28 bladder cancer cell line." (PMID 37147328, 2023). "However, EP300 mutation did not remain statistically significance after taking into account age, gender, grade, TNM classification and TMB status in Cox regression model, suggesting that EP300 mutation might not be an independent risk factor of prognosis in bladder cancer patients." (PMID 32012118, 2020).
diffuse large B-cell lymphoma (23 papers, 2014 to 2025). "It is notable that the EP300/CREBBP pathway mutational signatures uncovered in this study are also seen in diffuse large B-cell lymphoma, where they are associated with NOTCH activation via negative regulation of FBXW738." (PMID 41162424, 2025). "In addition, inactivating mutations identified in the HAT gene EP300 have been implicated in a wide array of cancer types including diffuse large B cell lymphoma, head and neck, esophageal, colorectal, medulloblastoma and non-small cell lung carcinoma." (PMID 29084603, 2017). "In a Phase 2 study examining the efficacy of mocetinostat, an oral HDACi, researchers investigated its effects on patients with relapsed or refractory diffuse large B-cell lymphoma (DLBCL) or follicular lymphoma (FL) who have mutations in the CREBBP/EP300 genes." (PMID 40426926, 2025). "As previously reported for diffuse large B-cell lymphoma (DLBCL) and follicular lymphoma (FL), pathogenic variants involving the CREBBP and EP300 genes seem to arise particularly frequently in patients with cHL showing chemorefractory disease." (PMID 38473705, 2024). "Chromatin writers and erasers are frequently mutated in GC-derived lymphomas, mostly in diffuse large B cell lymphomas (DLBCLs) that show prevalent mutations in major epigenetic modifiers such as EZH2, EP300, CREBBP and KMT2D." (PMID 35580618, 2022). "Consistently, another study demonstrated that low expression of CREBBP or EP300 inhibits H3K27 acetylation via the FBXW7–NOTCH–CCL2/CSF1 axis to induce the polarisation of tumour-associated macrophages to the M2 phenotype and tumour cell progression in diffuse large B-cell lymphoma (DLBCL)." (PMID 38493218, 2024). "In diffuse large B-cell lymphoma (DLBCL), CREBBP/EP300 mutations have been found to primarily affect the HAT-lysine acetyltransferase 11 (KAT11) domain." (PMID 36831561, 2023).
neuroblastoma (21 papers, 2014 to 2025). Neuroblastoma (NB) is the most common solid, extracranial childhood tumor. "A growth dependence on EP300 has also been observed in high-risk pediatric neuroblastoma, with EP300 degradation resulting in loss of MYCN and subsequent cell death." (PMID 39766049, 2024). "More recently, the histone acetyltransferase EP300 was found to maintain histone acetylation at enhancer sites in neuroblastoma, and small molecule–induced degradation of this target has antitumor activity in neuroblastoma murine models." (PMID 38820154, 2024). "Inhibition of CBP/CREBBP and EP300 activity in vitro and in vivo blocks tumor growth in neuroblastoma, pancreatic cancer, and acute myeloid leukemia." (PMID 37509254, 2023). "Additionally, clinically relevant germline variants were detected in four cancer-associated genes, including an SBDS splice-site mutation (c.258 + 2T > C) in a rhabdomyosarcoma, BARD1 p.E652fs*69 in a neuroblastoma, EP300 p.A2259fs*20, and EXT2 p.W414* in two osteosarcoma patients." (PMID 35585047, 2022). "Unlike EP300, in pediatric neuroblastomas, CBP/CREBBP plays a limited role but stimulates lung tumorigenesis via MAPK and CPSF4 signaling pathways, reducing survival and disease-free survival." (PMID 37509254, 2023). "Interestingly, several sequence alterations in other genes involved in chromatin regulation in neuroblastoma have been found, including EP300, CREBBP, TTF2, KDM5A, CHD9, and gene IKZF1, which might undergo somatic mutations and promote NB occurrence." (PMID 28055978, 2017). "While prior studies focused on EP300/CBP as a unit, a more recent study illustrated that neuroblastoma (NB) cells depend on EP300 but not CBP." (PMID 38914477, 2024).
Obesity (21 papers, 2013 to 2025). Accumulation of substantial excess body fat. "Although EP300 itself is only linked to obesity within the spectrum of metabolic and liver diseases, its neighbors are associated with additional phenotypes according to the Comparative Toxicogenomics Database (CTD)." (PMID 39399467, 2024). "Specifically, we observed elevated levels of KDM6A, CREBBP, and EP300 histone modifiers in ASCs from patients with obesity class II‐III." (PMID 40518865, 2025). "In the vWAT progenitor cells (ASCs), there was a substantial increase in CCL2 and an increase in the expression of KDM6A, as well as the acetylases CREBBP and EP300 in the patients with obesity." (PMID 40518865, 2025). "EP300 is also a key mediator of cellular homeostasis, making it an essential therapeutic target for obesity." (PMID 39208245, 2024). "The results of this study explain that the reduction in EP300 gene expression can be targeted to inhibit adipogenesis and be used to treat obesity." (PMID 39208245, 2024). "Combined with bioinformatics analysis, we identified EP300, a histone and lysyl acetyltransferase, as a master regulator for genes dysregulated in obesity and normalized by CR and RSV." (PMID 26441656, 2015). "The clustering revealed that HDAC2, CEBPB, and EP300 (Cluster 7) were transcriptional regulators for genes dysregulated in obesity and normalized by RSV and CR in both DIO zebrafish and obese human." (PMID 26441656, 2015). "The results of skyline query analysis showed that EP300, PPARG, and PPARGC1A were dominant and, therefore, have potential as targets for treating obesity." (PMID 39208245, 2024). "Integration analysis using a skyline query revealed three main targets, EP300, PPARG, and PPARGC1A, which are potential targets for fighting obesity." (PMID 39208245, 2024). "Moreover, C‐C motif chemokine 2 (CCL2) and KDM6A expression was higher in the group with obesity, as were CREBBP and EP300." (PMID 40518865, 2025). "While the direct influence of Ppargc1a on Ep300 has not been previously reported, the relationship from Ep300 to Ppargc1a is well-documented, where Ep300 acts as a co-activator, particularly in obesity and thermogenesis." (PMID 40924721, 2025). "Indeed, the binding regions of EP300, CEBPB, and HDAC2 in the promoters of transferrin (TF), insulin-like growth factor binding protein 1 (IGFBP1) and NQO1, whose expression was increased in obesity and was normalized by CR or RSV, overlap." (PMID 26441656, 2015).
cervical carcinoma (20 papers, 2015 to 2025). A carcinoma arising from either the exocervical squamous epithelium or the endocervical glandular epithelium. "Apart from these, mutations in ODZ1, TTN and EP300 are already reported in cervical cancer." (PMID 27829003, 2016). "Additionally, FBXW7 and EP300 mutations have already been reported in cervical cancer." (PMID 35205332, 2022). "The landmark studies by the Cancer Genome Atlas (TCGA) have reported that the most frequent mutations in cervical cancer are PIK3CA (26%), EP300 (11%), FBXW7 (11%), and PTEN (8%)." (PMID 37256181, 2023). "The most frequent significantly mutated genes (SMGs) across the 430 cervical carcinomas were previously reported and included PIK3CA (27%), KMT2C (also known as MLL3) (19%), KMT2D (also known as MLL2) (13%), EP300 (12%), FBXW7 (12%), FAT1 (8%), and PTEN (8%)." (PMID 34620846, 2021). "Accumulating studies have identified various genomic mutations of PIK3CA, EP300, FBXW7, PTEN, HLA-A, ARID1A and so on in different cervical cancer tissues." (PMID 32123519, 2020). "These pathways and the recurrently mutated genes involved therein, such as EP300, ARID1A, FBXW7, NFE2L2, PIK3CA, and ERBB2, were all found to be pathogenic in previous cervical cancer studies." (PMID 28390392, 2017). "Moreover, previous studies on the genomic landscape of cervical cancer have identified frequent alterations in genes, such as PIK3CA, EP300, FBXW7, and APOBEC signatures, associated with the process of carcinogenesis of virus-associated diseases." (PMID 37256181, 2023). "Furthermore, EP300, ARID1A, FBXW7, NFE2L2, PIK3CA, and ERBB2 have all been previously reported as pathogenic genes in cervical cancer, and we highlighted the roles of MLL2, MLL3, and CREBBP in the tumorigenesis." (PMID 28390392, 2017). "One recent study of 228 cervical cancers using TCGA data identified SHKBP1, ERBB3, CASP8, HLA-A, and TGFBR2 as novel significantly mutated genes, and previously identified pathogenic genes including PIK3CA, EP300, ARID1A, and NFE2L2 were also confirmed." (PMID 28390392, 2017). "In total, 28 genes (e.g., ATF2, BRCA2, CSRP2BP and EP300) were up-regulated and 16 genes (e.g., CDY1, CHAT and CRAT) were down-regulated in cervical cancer." (PMID 37845756, 2023).
Hyperglycemia (20 papers, 2010 to 2026). An increased concentration of glucose in the blood. "Impairment of DNM1 causes insulin secretion failure and hyperglycemia in mice while inhibiting the expression of EP300 reduces adiposity in larval zebrafish." (PMID 37620670, 2023).
liver cancer (20 papers, 2011 to 2025). An epithelial or non-epithelial malignant neoplasm that arises from the liver. "In our study, the result of stem cell microarrays showed that DTX1 and Ep300 were highly expressed in liver cancer stem-like cells." (PMID 21669008, 2011). "As TRIM71 is vital for maintaining the dedifferentiation of stem cells and regulate glycine/serine metabolism, we hypothesized the potential regulation of RXRA and EP300 on TRIM71 in liver cancers." (PMID 39267787, 2024). "Importantly, ATRA or A-485 decreased mRNA levels of TRIM71, CEBPA, PSPH, PSAT1 and protein levels of TRIM71 and CEBPA, suggesting the transcriptional regulation of RXRA and EP300 to TRIM71 in liver cancer." (PMID 39267787, 2024). "As glucose-mediated activation of the AMPK/EP300 axis favors EP300/β-catenin association and would be inhibited in the presence of high GYS2, we anticipated that in liver cancer, in which GYS2 levels vary considerably, high GSY2 activity would correlate with reduced β-catenin activity." (PMID 32603375, 2020). "To elucidate the molecular mechanisms underlying the overexpression of TRIM71 in liver cancer cells, we analyzed potential regulators binding on TRIM71 promoter regions using ENCODE database, and unexpectedly discovered the potential binding of retinoid X receptor alpha (RXRA) factor and EP300." (PMID 39267787, 2024). "EP300 and GCN5 showed higher occupancy on the GPNCA promoter region in liver cancer cells demonstrated by ChIP assays." (PMID 32029792, 2020). "Furthermore, we identified that all-trans-retinoic acid (ATRA) combined with e1A binding protein p300 (EP300) inhibitor A-485 repressed TRIM71, attenuated glycine/serine metabolism, and inhibited liver cancer cell proliferation with high TRIM71 levels." (PMID 39267787, 2024). "Furthermore, we identified that all-trans-retinoic acid (ATRA) and e1A binding protein p300 (EP300) inhibitor A-485 could repress TRIM71 expression, dampens glycine/serine/threonine metabolism, and inhibits liver cancer cell proliferation." (PMID 39267787, 2024).
glioma (19 papers, 2010 to 2025). A benign or malignant brain and spinal cord tumor that arises from glial cells (astrocytes, oligodendrocytes, ependymal cells). "EP300-BCOR fusion has been recently reported in a group of children with low-grade gliomas displaying divergent histological features including pilocytic astrocytoma or dysembryoplastic neuroepithelial tumor." (PMID 33718245, 2021). "The previously reported events include BCOR-CREBBP and CREBBP-BCOR fusions in ESS, and EP300-BCOR fusions in 3 cases of pediatric glioma." (PMID 32493417, 2020). "In contrast to IDH1-mutant gliomas, ATRX mutations associated with H3G34V, ZMYND11, EP300, or BRAF V600E were stable across the disease course in our study." (PMID 29084603, 2017). "The EP300 is located on chromosome 22q, and deletion of this gene is also common in gliomas." (PMID 33718432, 2021). "This indicates that EP300 may play a tumor suppressor role in glioma and EP300 (22q) may be one of the tumor suppressor genes lost in the 22q− event." (PMID 33718432, 2021). "More recently, EP300-BCOR alterations have been described in pediatric gliomas." (PMID 32493417, 2020). "We found that copy number deletions of EP300 were associated with lower EP300 mRNA expression levels, and reduced expression of EP300 in gliomas without EP300 CNVs was related to a worse clinical prognosis." (PMID 33718432, 2021). "Furthermore, we compared the BCOR-CREBBP fusion product in the present case to that of previously reported chimeric transcripts involving BCOR rearrangements with CREBBP or EP300 in ESS and pediatric gliomas." (PMID 32493417, 2020). "Therefore, we compared EP300 mRNA expression levels according to CNV status, as well as the OS rates between high and low levels of EP300 expression in gliomas without EP300 CNVs." (PMID 33718432, 2021).